SMCR5 (Smith-Magenis syndrome chromosome region, candidate 5)
Synonyms: NCRNA00034
Gene: Long non-coding RNA gene on chromosome 17 (17,776,686 to 17,779,529, reverse strand). Ensembl gene ENSG00000226746.
Diseases named in the same sentence as SMCR5 in open-access papers:
SMCR5 is named in the same sentence as 3 diseases in open-access papers, as found by Europe PMC text mining. Sharing a sentence is not in itself a finding about the gene and the disease. The quoted sentences say what the papers report.
gastric cancer (1 paper, 2020). A primary or metastatic malignant neoplasm involving the stomach. "Although there have been no reports on the relationship between LINC00052/SMCR5 and chemoresistance, high expression of LINC00052 was found to promote gastric cancer cell proliferation and metastasis and progression of head and neck squamous cell carcinoma." (PMID 33680916, 2020).
SMCR5 also shares sentences with these, for which no sentence is quoted: head and neck squamous cell carcinoma (1 paper); Smith-Magenis syndrome (1).